SPRR2C (small proline rich protein 2C (pseudogene))
Gene: Transcribed unprocessed pseudogene on chromosome 1 (153,140,491 to 153,140,709, reverse strand). Ensembl gene ENSG00000229035.
Diseases named in the same sentence as SPRR2C in open-access papers:
SPRR2C is named in the same sentence as 9 diseases in open-access papers, as found by Europe PMC text mining. Sharing a sentence is not in itself a finding about the gene and the disease. The quoted sentences say what the papers report.
psoriasis (8 papers, 2014 to 2024). An autoimmune condition characterized by red, well-delineated plaques with silvery scales that are usually on the extensor surfaces and scalp. "This study screened for lncRNAs both differentially expressed and in coexpression networks associated with psoriasis and response to treatment and identified lncRNA SPRR2C as a potential hub gene." (PMID 33452236, 2021). "Several lncRNAs might act as psoriasis biomarkers and/or therapy targets, such as the IL−22-responsive SPRR2C, psoriasis susceptibility gene PRINS, NF-κB-dependent ANRIL, IL−17A-promoting H19, and the innate immune response-related HOTAIR and MALAT1." (PMID 37310201, 2023). "Next, we performed a bioinformatics analysis to detect miRNAs that could be associated with SPRR2C function in the pathogenesis of psoriasis." (PMID 33452236, 2021). "Another IL−22-responsive lncRNA, SPRR2C was one of the most highly upregulated lncRNAs in psoriasis lesions and was identified as a psoriasis hub gene." (PMID 37310201, 2023). "As a skin-expressed lncRNA, SPRR2C is prominently induced in both psoriasis and atopic dermatitis lesions." (PMID 38002328, 2023). "SPRR2C has also been shown to play an important role in psoriasis pathogenesis and response to treatment." (PMID 35559048, 2022). "More importantly, SPRR2C expression in the tissue samples was positively correlated with the Psoriasis Area and Severity Index (PASI) scores in clinical cases." (PMID 33452236, 2021). "To further validate the correlation of STAT1 and S100A7 with SPRR2C in psoriasis, we next evaluated the STAT1 and S100A7 protein levels and distribution in the psoriatic lesional and normal control tissue samples." (PMID 33452236, 2021). "Here, lncRNA SPRR2C was reported to be a hub gene exerting a critical effect on the pathogenesis of psoriasis and response to treatment using both WGCNA and differential expression analyses." (PMID 33452236, 2021). "In addition, SPRR2C, a potential regulator that modulates IL-22 stimulation, was upregulated in both atopic dermatitis and psoriasis lesional skin and was also downstream of the IL-17A and IL-17 + TNF signaling in keratinocytes." (PMID 35559048, 2022). "To investigate the specific effects of SPRR2C, we stimulated human immortalized keratinocytes (HaCaT cells) with IL-22 (100 ng/ml) for 24 h to mimic the in vitro pathological changes in psoriasis, conducted SPRR2C knockdown in HaCaT cells, and then examined related indexes." (PMID 33452236, 2021). "In this study, we identified lncRNA SPRR2C (small proline-rich protein 2C) as a hub gene with a critical effect on the pathogenesis of psoriasis and response to treatment using both weighted gene coexpression network analysis (WGCNA) and differential expression analysis." (PMID 33452236, 2021). "Several lncRNAs are upregulated in psoriasis, such as MSX2P1, XIST, FABP5P3, KLDHC7B-DT, or SPRR2C, whereas MEG3, GAS5, PRINS or NEAT1 are downregulated in psoriasis." (PMID 38256115, 2024). "Other upregulated lncRNA in psoriasis are MIR31HG, MSX2P1, XIST, FABP5P3, KLDHC7B-DT, or SPRR2C; whereas, MEG3, GAS5, PRINS or NEAT1 are downregulated in psoriasis." (PMID 37628670, 2023). "Prominent skin-expressing lncRNAs that were upregulated in both psoriasis and atopic dermatitis lesional skin include UCA1 and SPRR2C (small proline rich protein 2C)." (PMID 35559048, 2022). "Examples of KC-assigned genes strongly elevated in psoriasis lesions included SERPINB4, SPRR2C and SERPINB3." (PMID 24885462, 2014). "Interestingly, the expression of SPRR2C is considerably increased in the non-lesional skin of both psoriasis and atopic dermatitis but to a lesser extent than in lesional skin." (PMID 38002328, 2023).
Barrett esophagus (2 papers, 2014 to 2021). Esophageal lesion lined with columnar metaplastic epithelium which is flat or villiform. "For example, miR-196a has been studied for its oncogenic roles in glioblastoma, pancreatic adenocarcinoma, breast cancer, oesophageal adenocarcinoma, and colorectal cancer, and shown to target HOX family genes (HOXA7, HoxB7, HOXC8, HOXB8, HOXD8), ERG, HMGA2, ANXA1, S100A9, SPRR2C, KRTS." (PMID 24621885, 2014).
tumor (1 paper, 2021). "Moreover, miR-196a promoted tumor progression by down-regulation of SPRR2C, S100A9 and KRT5." (PMID 33289788, 2021).
SPRR2C also shares sentences with these, for which no sentence is quoted: atopic dermatitis (1 paper); breast carcinoma (1); colorectal cancer (1); dysplasia (1); glioblastoma (1); pancreatic adenocarcinoma (1).